PTPN13 (protein tyrosine phosphatase non-receptor type 13)
Diseases named in the same sentence as PTPN13 in open-access papers (continued):
Sharing a sentence is not in itself a finding about the gene and the disease.
tumor (continued). "The nonreceptor protein tyrosine phosphatase, PTPN13 (also known as FAP1, PTPL1, PTPLE, PTPBAS, and PTP1E) has recently been considered as a putative tumor suppressor." (PMID 24191246, 2013). "In addition, CRC samples with high PTPN13 expression had significantly fewer CD8+ T cells within the tumor microenvironment." (PMID 41486293, 2026). "Furthermore, Ptpn13 knockdown in tumor cells significantly enhanced the expression of the effector cytokines IFNγ and TNFα in CD8+ T cells isolated from CT26-shApc tumors in WT Balbc mice, indicating an increase in CD8+ T cell effector function." (PMID 41486293, 2026). "In summary, using loss- and gain-of-expression approaches, we demonstrated that PTPN13 acts as a tumor suppressor in HGSOC cell lines; it inhibits tumor aggressiveness by regulating SNAIL, SLUG, and ZEB-dependent EMT, and also sensitizes these cell lines to platinum salts." (PMID 37895093, 2023). "Then, to validate our initial results on PTPN13 prognostic and predictive value, we assessed PTPN13 expression with digital droplet PCR (ddPCR) using RNA extracted from tumor sections of a new series of 60 HGSOC samples for which follow-up data (recurrence) were available." (PMID 37895093, 2023). "In clear cell renal cell carcinoma, PTPN3 and PTPN13 act as tumor suppressors by inactivating the AKT signaling pathway, whereas PTPN12 restrains the proliferation of renal cell carcinoma by inhibiting PI3K/mechanistic target of rapamycin (mTOR) pathway activity." (PMID 35957898, 2022). "Our results thus indicate a tumour suppressor role of PTPN13 in the early stages of CRC growth, while in serosal invasion it may act as a tumour promoter via activation of Slug and Snail and inhibition of FAS-induced apoptosis." (PMID 36140249, 2022). "Taken together, these results reveal that PTPN13 could be a key factor in antitumor activity, especially inhibiting tumor growth, against HCC in vitro and in vivo." (PMID 33051595, 2021). "Thus, our results suggest that PTPN13 is a tumor suppressor in HCC and a potential therapeutic target." (PMID 33051595, 2021). "To extend our knowledge on PTPN13-mediated tumor invasion regulation specifically in TNBC, we generated isogenic MDA-MB-231 cell clones that overexpress wild type (wt) PTPN13 (three clones: N13-1, -2 and -3) or a catalytically inactive mutant (one clone: CS) using the Flp-In system." (PMID 31938048, 2020). "Thus, in solid cancers, PTPN13 inhibits primary tumor cell invasiveness through inhibition of the uPA system, regulation of the main EMT genes, and stabilization of cell junctions." (PMID 33322542, 2020). "Collectively, these data indicate that PTPN13 inhibits tumor aggressiveness and that its catalytically-inactive mutant may act as a dominant-negative variant that promotes tumor aggressiveness." (PMID 31938048, 2020). "Although previous clinical studies on PTPN13 expression in various tumor types argued for a tumor suppressor role, its exact role in tumorigenesis remains unclear due to its negative contribution to FAS receptor-induced apoptosis 8,26." (PMID 31938048, 2020). "Furthermore, PTPN13 repression mediated by miR-200 increases sensitivity to FAS-induced apoptosis in tumor cell lines with mesenchymal features (see chapter A)." (PMID 33322542, 2020). "Altogether, these data bring weight to the hypothesis of a primary tumor suppressor role for the PTPN13 phosphatase." (PMID 33322542, 2020). "Finally, we present future research axes following recent findings on its role in cell junction regulation that implicate PTPN13 in cell death and cell migration, two major hallmarks of tumor formation and progression." (PMID 33322542, 2020). "However, other studies suggest that PTPN13 acts as a tumor promoter via inhibition of Fas-induced apoptosis, or by undefined mechanisms in Ewing's sarcoma." (PMID 29221157, 2017).
tumor (continued). "When Necl-4 does not sufficiently inhibit the dimerization of ErbB3 with ErbB2, PTPN13 may complement the tumour suppressive function of Necl-4." (PMID 28900130, 2017). "Patients with high tumor expression of PTPN13 may particularly benefit from APC11-based therapies." (PMID 41486293, 2026). "Thus, we have identified a previously unknown APC/PTPN13/STAT1-dependent tumor immune-suppressive mechanism." (PMID 41486293, 2026). "In summary, depending on the tumor type, PTPN13 may regulate resistance to anti-cancer therapies through its anti-apoptotic role via the FAS pathway, or through regulation of secondary EGFR pathways (ephrinB1/ErbB and SRC/PKD1/AKT), or through an indirect action on microtubules mediated by ephrinB1." (PMID 33322542, 2020). "On the other hand, PTPN13 is involved in proteostasis-regulating processes (e.g., proteosomal degradation 63 and autophagy 64) that are crucial determinants of cell-matrix 65 and cell-cell 66,67 interactions and consequently can affect tumor cell dissemination." (PMID 31938048, 2020). "These inhibitory effects of PTPN13 on cell movement may account for its tumor-suppressive role." (PMID 25893857, 2015). "This is because the APC11 peptide mimics the effect of APC overexpression, which can further enhance the inhibition of PTPN13 and the activation of IFNγ-STAT1 signaling in APC intact tumor cells, thereby enhancing the immune response." (PMID 41486293, 2026). "PTPN13 and PTPN14, protein tyrosine phosphatases, modulate key signaling pathways involved in tumor progression and metastasis." (PMID 40952239, 2025). "A number of Protein Tyrosine Phosphatases (PTPs) have been described in human cancers as tumour suppressor genes and among the most studied include PTPRM;, PTPN13; and PTPRG;." (PMID 38475971, 2024). "First, we observed downregulation of miR-200b, PTPN13 and ZEB2 in CRC with serosal invasion (pT4a) compared to pT3 tumours." (PMID 36140249, 2022). "In lymph node metastases compared to the invasive front of the tumor, ONECUT2 and SOX2 were down-regulated, while PTPN13, TGFB2, ZEB2, RND3 and CDKN1B were up-regulated." (PMID 34046357, 2021). "SRC, ephrinB, EGFR, and HER2 signaling are inhibited by PTPN13 that limits anchorage-independent cell growth (SRC), cell proliferation (HER2 and EGFR), and also invasion and tumor aggressiveness (SRC, HER2)." (PMID 33322542, 2020). "Expression of wt or mutant PTPN13 did not modify cell growth or apoptosis compared with control (pFRTLacZeo vector alone; Mock), but significantly affected cell motility and invasiveness (i.e., two biological parameters associated with tumor cell aggressiveness)." (PMID 31938048, 2020). "Similarly, phosphorylation of ERK was not significantly different in cells and tumors expressing wt or mutant PTPN13 compared with Mock.Thus, no indications were obtained that PTPN13's tumor suppressor activity is associated with ERK, AKT and Src inactivation in this model." (PMID 31938048, 2020). "Previous studies reveal that PTPN13 probably mediates regulation of cell homeostasis through PI3-kinase-dependent signaling pathways, and suppresses tumor aggressiveness through the inactivation of Src kinase (dephosphorylation)." (PMID 27285768, 2016). "We found substantial changes of both DNA methylation and mRNA expression of CR1, ESR1, PTPN13, and SOCS2 in HCCs compared with paired non-tumor tissues, which is consistent with the results obtained by analyzing the array data in our discovery sample." (PMID 25965583, 2015). "For example, the non-receptor protein tyrosine phosphatase, PTPN13 (also known as FAP1, PTPL1, PTPLE, PTPBAS, PTP1E; PTP-BL is the mouse homolog) has recently been dubbed a putative tumor suppressor." (PMID 22279592, 2012). "Ptpn13 knockout significantly suppressed the growth of subcutaneously grafted CT26-shApc cells in Balb/c mice and improved mouse survival in an intraperitoneal tumor implantation model." (PMID 41486293, 2026).
tumor (continued). "Furthermore, SHROOM4 appears to regulate the tumor microenvironment (TME) through mechanisms such as angiogenesis and cell cycle modulation mediated by ANGPTL7 and PTPN13 in LUAD, thereby influencing cancer progression." (PMID 41573567, 2025). "PTPN13 consists of multiple of PDZ domains and functions as a tumor suppressor." (PMID 39395036, 2024). "Another noteworthy gene is protein tyrosine phosphatase, non-receptor type 13 (PTPN13), which is known to induce apoptosis and restrict proliferation in tumor cells." (PMID 39906740, 2024). "After dividing the tumor samples into two groups based on PTPN13 expression (cut-off lower tercile), we observed a non-significant trend towards longer recurrence-free survival in patients with high PTPN13 expression (HR = 1.27; p = 0.33)." (PMID 37895093, 2023). "In addition, PTPN13 seems to be one of the important regulators involved in serosal invasion, and ONECUT2 in tumour growth." (PMID 36140249, 2022). "We analyzed the expression levels of PTPNs in the TCGA database and discovered that PTPN1, PTPN6, PTPN7, PTPN18, PTPN20, and PTPN22 were significantly upregulated in tumor samples, while PTPN4, PTPN5, PTPN10, PTPN11, PTPN13, PTPN14, and PTPN21 were downregulated in tumor samples." (PMID 36226189, 2022). "Protein Tyrosine Phosphatase Non-Receptor Type 13 (PTPN13) belongs to the non-receptor tyrosine phosphatases that functions as a tumor suppressor in NSCLC." (PMID 35264191, 2022). "Tyrosine-protein phosphatase nonreceptor type 13 (PTPN13) is a significant regulator in tumor development, however, its specific role in hepatocarcinogenesis remains to be explored." (PMID 33051595, 2021). "As PTPN13 was a candidate tumor suppressor for HCC, we examined whether the transient re-expression of PTPN13 (shOE) could reverse the enhancement on HCC cell growth induced by silencing PTPN13 expression (shPTPN13)." (PMID 33051595, 2021). "While there are no available data about the expression of PTPN13 (miR-200c target) in metastases, a number of its potential interacting partners point to its role in tumor progression, including modification of cell shape, motility and cell signaling." (PMID 34046357, 2021). "Specifically, PTPN13 has been shown to be involved in a negative feedback mechanism with Her2 activity, affecting the invasiveness of Her2 tumor cells." (PMID 34265306, 2021). "In hematopoietic malignancies, PTPN13 promotes, through β-catenin, HSC adhesion to their niche, which may later lead to tumor cell invasion." (PMID 33322542, 2020). "Although the number of mammary nodules was similar in tumors from both strains, lack of catalytically active PTPN13 promotes number of tumor localizations per mouse." (PMID 31938048, 2020). "Moreover, expression of some PTP tumor suppressors, such as PTPRD, PTPRO, PTPN12, PTPN13 and DUSP1, is reduced due to epigenetic silencing." (PMID 29558404, 2018). "Analysis of tumors from ApcMin/+/Ptpn13fl/fl/Vil-CreERT2 (APV) mice showed that Ptpn13 knockout, induced by TAM treatment, significantly upregulated the expression of IRF1, LMP2, TAP1, TAP2, H2-D1, H2-K1, and B2M and also increased the surface levels of MHC-I complex on tumor cells." (PMID 41486293, 2026). "This included hypermethylation of negative TMRs associated with tumour suppressor genes, such as TGFBR2 and SMAD3, as well as loss of methylation at negative TMRs for the oncogenes ERBB3 and SND1 and for PTPN13, which is described as having both oncogenic and tumour suppressor roles." (PMID 41036619, 2025). "PTPN13 (also known as FAP-1, Fas-associated phosphatase-1), a non-receptor protein tyrosine phosphatase, primarily inhibits pro-tumor signaling pathways such as PI3K/Akt and MAPK, thereby suppressing tumor cell proliferation and survival." (PMID 40308576, 2025).
tumor (continued). "Knockout (KO)(Kura-A3 and Kura-B1) or knockdown (KD)(Kura-A2) of PTPN13 in KURAMOCHI cells did not modify cell growth, but significantly increased cell migration and invasiveness, two biological parameters associated with tumor cell aggressiveness." (PMID 37895093, 2023). "Tumor samples of Inserm series were predicted in 2 and 4 subtypes molecular classification using a predictor based on nine genes: ADAM19, ETS1, and PDCD1LG2 for C1 and C2; CLDN1, DSC3, and SLC24A3 for C1A and C1B; CHL1, ECM2, and PTPN13 for C2A and C2B subtype prediction." (PMID 32083805, 2020). "Unlike hematopoietic cancers where PTPN13 negative transcriptional regulation has an anti-tumor effect by sensitizing cells to FAS-induced apoptosis, PTPN13 negative transcriptional regulation in solid cancers has a pro-tumor effect through activation of proliferation pathways." (PMID 33322542, 2020). "We next randomly selected 8 genes aberrantly expressed in HCCs that had aberrant DNA methylation (CR1, ESR1, PTPN13, and SOCS2) or SCNA (C8A, CXCL14, ITGA6 and MARCO) to validate the array-based results in an independent sample set consisting 47 HCCs and paired non-tumor specimens." (PMID 25965583, 2015). "The non-receptor phosphatase, PTPN13, has recently been dubbed a putative tumor suppressor." (PMID 22279592, 2012). "Noteworthy, many mechanistic studies that indicate a negative role of PTPN13 in FAS-induced apoptosis and suggest a pro-tumor function were performed in hematopoietic cancers." (PMID 33322542, 2020). "Overexpression of PTPN13 in HCC cell lines MHCC97H and HepG2 significantly reduced phosphorylation of ERK1/2 and STAT3 but not Src, indicating that PTPN13 may act as a tumor suppressor via ERK1/2 and/or STAT3 signaling in HCC." (PMID 29558404, 2018).
cancer (47 papers, 2004 to 2026). A tumor composed of atypical neoplastic, often pleomorphic cells that invade other tissues. "A mutational analysis of data from a tyrosine phosphatome-wide study of 157 CRC samples showed that PTPN13 is the second most commonly mutated phosphatase in these cancers (n = 15 tumors with a mutation; 9% of the entire sample)." (PMID 33322542, 2020). "In addition to genetic polymorphisms, epigenetic regulation of PTPN13/PTPL1 expression has been demonstrated in cancers." (PMID 38766487, 2024). "Loss of PTPN13 expression also has been associated with increased invasiveness in cancers." (PMID 39576841, 2024). "Finally, genetic studies support the notion of PTPN13 loss of expression/function in cancer, through LOH and/or SNPs." (PMID 33322542, 2020). "Twelve SNPs were located within gene regions, corresponding to nine genes, among which PTPN13 and TIAL1 are associated with cancer and immune function (Table A6)." (PMID 40427243, 2025). "The waterfall plot showed mutations landscape of PTPNs in 33 types of cancer and the bar chart displays the CNV profile of PTPNs, and provided the classification of CNV types, and PTPN13 was the most frequently mutated gene." (PMID 37884566, 2023). "This interaction, which is promoted by human papilloma virus 16 (HPV16) (known to inhibit PTPN13 in this cancer type), activates the MAPK pathway." (PMID 33322542, 2020). "Then, we describe PTPN13 clinical significance as a prognostic marker in different cancer types and its impact on anti-cancer treatment sensitivity." (PMID 33322542, 2020). "This gives also deeper insights into the mechanism how PTPN13 can regulate Fas sensitivity in cancer." (PMID 31308371, 2019). "As the PTPN13 gene is located on chromosome 4q that is frequently deleted in HGSOC and is a prognostic marker of survival in some cancers, we investigated PTPN13 expression profile in two cohorts of HGSOC samples by RT/PCR and by IHC, respectively." (PMID 29221157, 2017). "PTPN13 expression was down-regulated in Lung squamous carcinoma, and was negatively correlated with the cancer grade and stage." (PMID 27285768, 2016). "PTPN13 is involved in regulating cell death and migration, and its dysregulation in various cancers suggests that it may influence ALV-J infection by modulating immune responses and intracellular signaling pathways." (PMID 40427243, 2025). "Therefore, we overexpressed PTPN13 expression to counteract the cancer‐promoting effects of the overexpressed METTL1 and FOXM1." (PMID 38967523, 2024). "As PTPN13 induces resistance to FAS-mediated apoptosis, several studies evaluated whether resistance to cancer treatment is associated with PTPN13 expression." (PMID 37895093, 2023). "Compared with healthy tissues, PTPN13 expression is decreased in different types of cancer." (PMID 36140249, 2022). "By querying TCGA resource, it can be easily noted that the host gene of hsa_circ_0070354 (PTPN13) show negative association with cancer prognosis (HR<1), which is contrary to hsa_circ_0070354 (HR>1)." (PMID 35096013, 2021). "Moreover, in ccRCC cell lines and xenografts, PTPN13 overexpression restricts cancer cell proliferation and invasion through Akt inactivation." (PMID 33322542, 2020). "As PTPN13 induces resistance to FAS-mediated apoptosis, several studies evaluated whether resistance to cancer treatment is associated with PTPN13 expression (see chapter 2.1)." (PMID 33322542, 2020). "PTPN13 is also involved in the regulation of cancer cell migration/invasion via its partner and substrate thyroid hormone receptor interactor 6 (TRIP6, also called ZRP-1) that promotes cell mobility induced by lysophosphatidic acid, and activates Wnt/β-catenin signaling." (PMID 33322542, 2020). "The modeling results may contribute to intensively understanding on the biological role of PTPN13, as the first phosphatase able to inhibit Src through direct dephosphorylation in cancer cells." (PMID 27285768, 2016).